ALB (albumin)
Diseases named in the same sentence as ALB in open-access papers (continued):
Sharing a sentence is not in itself a finding about the gene and the disease.
tumor (continued). "For manifest malignant disease, inflammation based scores using more classic inflammatory markers as CRP or albumin indeed have been shown to have prognostic value, independent of tumour entity or stage." (PMID 31463975, 2019). "Tumor cells can take up human serum albumin through endocytosis; therefore, albumin-based nanoparticles can show high stability without cytotoxicity." (PMID 31470511, 2019). "Based on our small animal 99mTc-albumin nanoparticle SPECT tumorous liver study results, we suggest the use of skewness of liver activity distribution histogram to characterize the inhomogeneity of the whole organ due to tumor infiltration." (PMID 31346827, 2019). "In their design, the engineered T lymphocytes can act as a shuttle to efficiently deliver doxorubicin–albumin conjugates to peripheral cells of the tumor but not the tumor core region." (PMID 31817418, 2019). "Abraxane, an albumin-bound PTX, was modified with LyP-1 or CREKA via their cysteine sulfhydryl group using a sulfo-SMCC cross-linker to evaluate the inhibition of tumor growth in tumor-bearing mice with MDA-MB-435 cells." (PMID 30905205, 2019). "We measured the expression of six different Zn-binding proteins in tissue microarrays (TMAs) from OPSCC patients by IHC in matched tumor and normal tissue, including: Lipocalin-1 (n = 63), AZGP1 (n = 68), albumin (n = 26), S100A7 (n = 53), S100A7 (n = 53), S100A8 (n = 51) and S100A9 (n = 50)." (PMID 31740720, 2019). "Univariate analysis indicated that metastasis, CA19-9, TBIL, and SII were prognostic factors for OS in the training cohort, whereas age, gender, tumor location, ALB, ALP, ALT, and AST had no prognostic value for OS." (PMID 30658662, 2019). "However, predisposing factors include increased MTD, with increased levels of the HCC plasma tumor markers des-gamma carboxyprothrombin (DCP) and AFP, decreased serum albumin, and elevated platelet counts." (PMID 30009156, 2018). "For example, whereas for platinum (II)-based drugs such as cisplatin binding to serum proteins, especially human serum albumin (HSA) leads to deactivation and lower bioavailability of the drug, other concepts exploit HSA for targeted drug delivery to the tumor tissue." (PMID 30155703, 2018). "There were significant intergroup differences in age (year), number of tumors, maximum tumor diameter (mm), CRP (mg/dL), albumin (g/dL), globulin (g/dL), WBC count (×103/mm3), platelet count (×104/mm3), CEA (ng/mL), CA19‐9 (U/mL), and NLR (Mann–Whitney U‐test)." (PMID 30460347, 2018). "In addition to perioperative blood transfusion, significant prognostic factors included: age, tumor size, tumor location, TNM stage, type of gastrectomy, operation time, albumin level at admission, and hemoglobin level at admission." (PMID 29890957, 2018). "A tumor-to-kidney ratio of accumulated activity in the range of 0.1–0.2, as was the case for conventional folate radioconjugates (without albumin binder), prevented the realization of the therapeutic concept completely." (PMID 29914162, 2018). "Only 20 patients (8.7%) had tumor recurrences and 8 patients (3.5%) did not survive in the group of patients with a post-operative serum albumin level ≥ 32 g/L." (PMID 30522461, 2018). "During follow-up, 30 patients (30.3%) had tumor recurrences and 24 patients (24.2%) did not survive in the group of patients with a post-operative serum albumin level < 32 g/L." (PMID 30522461, 2018). "The results of our analysis showed that the PNI value correlated significantly with lymphocyte count (p < 0.0001), tumor size (p = 0.0327), depth of tumor (p < 0.0001), TNM pStage (p = 0.0005), SCC antigen level (p = 0.0072), albumin level (p < 0.0001), and CRP level (p = 0.0012)." (PMID 29290069, 2018).
tumor (continued). "With a highest C‐index and areas under the receiver operating characteristic curve (AUC), C‐reactive protein/albumin ratio (CAR) was selected to construct the novel system, along with tumor number, tumor size, macrovascular invasion and extra‐hepatic metastases." (PMID 30259688, 2018). "Furthermore, the ABP‐HBVC retained in tumor for much longer period of time, compared to the ABP‐free HBVC, which reportedly seems to be due to the long half‐life of ABP that binds to serum albumin that is a major energy and nutrition source for tumor growth." (PMID 30128257, 2018). "The albumin-NLR was the only inflammation score type found to predict OS, indicating that this measure may better reflect the status of the local tumour-infiltrating inflammatory cells." (PMID 30419863, 2018). "This is, however, a rather moderate effect in comparison to the previously shown effect of PMX on conventional radiofolates (without albumin binder), which led to 5–6-fold increased tumor-to-kidney ratios." (PMID 29914162, 2018). "The Mann–Whitney U‐test revealed significant intergroup differences in age; maximum tumor size (cm); PNI; the serum levels of albumin (g/dL), CA19‐9 (U/mL), CEA (ng/mL), CRP (mg/dL), and globulin (g/dL); survival period (day); and white blood cell count (×103/mm3)." (PMID 30238078, 2018). "In contrast, there was not a significant correlation between the serum level of LDH and tumour location, age, sex, KPS, metastasis (intrahepatic or extrahepatic), location of intrahepatic metastasis (right, left, or both lobes), albumin or PLR, similar to the findings for the test cohort." (PMID 28345594, 2017). "The variables tested by univariate analysis were sex, age, tumor size, α-fetoprotein (AFP), total bilirubin (TB), albumin (A), alanine aminotransferase (ALT), aspertate aminotransferase (AST), γ-glutamyl transferase (GGT), prothrombin time (PT), and HBVDNA status." (PMID 28700480, 2017). "A multivariate analysis disclosed that male gender, serum albumin ≤4.0 g/dL, bilirubin >1.6 mg/dL, a serum AFP level >20 ng/mL, a tumor size >3 cm, the presence of vascular invasion, as well as the presence of EGV, were the independent risk factors associated with poor OS rates." (PMID 28209963, 2017). "Strategies to enhance drug penetration and retention in the tumor bed have been actively pursued in the clinic and proved to be effective as in the case of nab-paclitaxel, the first FDA-approved drug conjugate made of paclitaxel bound to albumin particles." (PMID 27779106, 2017). "Our study demonstrated that BChE and albumin are robust prognostic factors for overall survival in treatment-naïve cancer patients without manifest hepatic involvement irrespective of tumor entity and stage." (PMID 29113384, 2017). "Subsequently, concise preparations of [67Cu]-labeled albumin and anti-IGSF4 antibody (anti-tumor-targeting antibody) could be achieved with DOTA being a more superior chelator to the Cu2+ metal than NOTA." (PMID 28507297, 2017). "The remaining components of the IGF-CTP classification were not significantly related to tumor stage (P = .11 for total bilirubin; P = .33 for albumin; and P = .39 for PT)." (PMID 28107416, 2017). "The multivariable Cox regression model showed that the key variables influencing survival were related to tumour characteristics (tumour size, tumour number, AFP and VI; P<0.0001), liver function (albumin and bilirubin) (P<0.0001), aetiology (P=0.0082) and age (P=0.0012)." (PMID 28125820, 2017). "Inhibition of EphB4 forward signaling using soluble EphB4 protein fused with murine serum albumin failed to affect eRMS model tumor progression, but did moderately slow progression in murine aRMS." (PMID 28817624, 2017). "In accordance to previous studies, we found decreasing BChE and albumin levels with progressing tumor stage for both the total cohort and patients without hepatic involvement." (PMID 29113384, 2017).
tumor (continued). "Compared to those without MVI, patients with MVI had lower serum albumin (P = 0.010), and larger tumor size (P < 0.001)." (PMID 28095820, 2017). "By univariate analysis, significant risk factors for the reduced survival of stage B patients included serum albumin level, AFP, PIVKA-II, AP-factor, anatomical resection, blood loss, tumor number, microscopic portal vein invasion, and a noncancerous liver." (PMID 28830473, 2017). "To enhance the anti-tumor effects of Ats at low concentrations, we tried to design novel Ats-loaded bovine serum albumin (BSA) NPs." (PMID 28610396, 2017). "Neither CpG + Trp2 nor anti-PD-1 alone significantly inhibited tumor progression, whereas albumin/AlbiVax inhibited the deposition and progression of lung metastases." (PMID 29203865, 2017). "Although increased macropinocytic uptake and lysosomal degradation of the most abundant serum protein, albumin, in Ras-transformed cells can meet these demands, it is not understood how the majority of tumor cells that express wild type Ras achieve this." (PMID 27974681, 2017). "When those patients were included for the analysis of factors associated with OS, univariate analysis showed that total bilirubin (TBIL), ALB, AFP, Child-Pugh score, tumor size, TNM stage, PD1 +8669 A/G and TIM3 −1516 G/T polymorphisms were significantly associated with patients' survival." (PMID 27034168, 2016). "The univariate survival analysis revealed the following predictors of mortality in patients with solitary large HCC: serum albumin < 4 g/dL, bilirubin ≥ 1 mg/dL, α-fetoprotein (AFP) level ≥ 400 ng/mL, performance status ≥ 1, tumor size > 10 cm, presence of PVTT, and TACE treatment (all p<0.01)." (PMID 27176037, 2016). "Univariate survival analysis for patients in the propensity score model showed the following predictors of poor prognosis: age < 65 years, serum albumin < 4 g/dL, bilirubin ≥ 1 mg/dL, AFP level ≥ 400 ng/mL, tumor size > 10 cm, presence of PVTT, and TACE treatment (all p<0.1)." (PMID 27176037, 2016). "The pre-albumin was not significantly correlated with gender, age, BMI, albumin, and tumor location." (PMID 27809860, 2016). "We found that eHSA supplement reduced the anticancer effect of DDP/VP-16 without altering blood albumin level as compared with the corresponding monotherapy group in mice with tumor." (PMID 27895586, 2016). "In particular, the ITA.LI.CA tumor staging showed a higher discrimination ability than UNOS TNM staging and HKLC staging, and CPS had a higher prognostic power than MELD score and the new albumin—bilirubin grade." (PMID 27116206, 2016). "These included serum concentration of total bilirubin and serum albumin level, parameters of Child-Pugh grade, which can reflect the residual hepatic function of the patients with HCC; and tumor stage (tumor size, portal vein thromboses, and number of liver lesions)." (PMID 27387757, 2016). "Univariate Cox proportional hazard analysis revealed that PLR, serum albumin, FIGO stage, tumor differentiation, PLN, and LVSI, but not NLR, were associated with OS and DFS." (PMID 26885692, 2016). "Albumin is accumulated in tumor tissue based on the EPR effect, which, however, is not reflected in cell culture settings." (PMID 26988975, 2016). "In addition, age, tumor size, venous invasion, Child-Pugh status, TNM stage, AFP, GGT, ALB, and ALT remained significant recurrence predictors." (PMID 26656354, 2015). "Univariate log-rank analysis identified the following factors as adverse influences on OS: presence of symptoms, decreased albumin levels, elevated alkaline phosphatase and CEA levels, tumor size >5 cm, positive surgical margin and lymph node status, and SPHK1 immunostaining." (PMID 26090720, 2015). "Albumin-based nanoparticles can accumulate in tumor by both the “EPR” (enhanced permeability and retention) effect and the interaction with the gp60 receptor expressed on the surface of tumor cells." (PMID 28793739, 2015).
tumor (continued). "Unlike in the Albumin-Cre/MST1fl/fl/MST2fl/fl model, arteries in the tumor-free background liver were not increased, but rather they remained stable, showing an appearance similar to that of wild-type mice." (PMID 26131558, 2015). "In addition, age, tumor size, venous invasion, Child-Pugh status, TNM stage, AFP, GGT, ALB, and ALT remained significant death predictors." (PMID 26656354, 2015). "Serum albumin levels did not vary significantly with sex, age, tumor size, degree of resection, MGMT promoter methylation and IDH1-R132H mutation status." (PMID 25880463, 2015). "The ‘albumin’ in nab-paclitaxel interacts with secreted protein acidic and rich in cysteine (SPARC), a matrix glycoprotein that has a role in tumor invasion and facilitates the uptake of paclitaxel by the tumor cells." (PMID 25935754, 2015). "Collectively, among the tumor models we tested, the LLC-implanted ectopic liver tumor and Albumin-Cre/WW45fl/fl mice seem to be models that most closely resemble the hemodynamic features of human HCC and are therefore appropriate for hemodynamic and/or radiological translational studies." (PMID 26131558, 2015). "Our results found novel cutoff points, such as serum-AFP of 7.5 ng/ml, -CEA of 5.2 ng/ml, -CA199 of 40 U/L, -ALB of 37.3 mg/ml, -GGT of 54 U/L, -ALT of 50 U/L, -ALP of 113 U/L, tumor size of 4 cm, MRP8 number of 8, MRP8 ratio of 0.0498, MRP14 number of 5, and MRP8 ratio of 0.0025." (PMID 26472105, 2015). "With continued tumor growth at 3 and 4 weeks post tumor inoculation, a significant increase in albumin staining occurred such that the disruption was no longer just in the immediate tumor vicinity but had spread to the contralateral side." (PMID 24818961, 2014). "DCE-MRI with an MMCA, albumin-Gd-DTPA, enabled the noninvasive acquisition of high-resolution 3D tumor angiograms (macrovasculature) as well as determination of the functional microvascular tumor parameters." (PMID 24466160, 2014). "After superimposing the albumin colloid study and both microsphere studies, ROIs were drawn to define tumor (regions of low uptake on the albumin colloid scan) and normal liver areas (a sampled area of uniform high uptake on the albumin colloid scan)." (PMID 24466071, 2014). "It has also been proposed that albumin carriers take advantage of the presence of albondin on the endothelium and SPARC in the tumor interstitium to increase the accumulation of drugs in the tumor space." (PMID 25161624, 2014). "At 2, 3 or 4 weeks following tumor cell inoculation, non-treated animals were perfusion fixed for immunohistochemical detection of Albumin, SP and NK1 receptor." (PMID 24818961, 2014). "The cells of the tumor in the present study were positive for C-KIT, EpCAM and E-cadherin, but negative for other known HPC markers including AFP, K19, CD34, CD56, CD133 and albumin." (PMID 25202388, 2014). "Indeed, using the prototypic macromolecular CA albumin-(Gd-DTPA), others have demonstrated that contrast enhancement correlated with histologic tumor grade in preclinical models." (PMID 25296030, 2014). "Albumin has non-toxic, non-immunogenic, biocompatible and biodegradable properties and has demonstrated preferential tumor uptake in various tumor xenograft animal models." (PMID 23291656, 2013). "Results showed that 30 days of β-carotene treatment could significantly inhibit tumour growth, enhance blood NK, IL-2, TNF-α, WBC, TP, ALB and A/G levels, and decrease blood ALT, AST and ALP activities in HCC rats." (PMID 22810193, 2012). "The inflammation-based Glasgow Prognostic Score (GPS), based on serum levels of CRP and albumin, has repeatedly been shown to be a predictor of survival, independent of tumor stage, performance status and treatment." (PMID 23092358, 2012). "Clathrin heavy chain si-RNA used to inhibit clathrin-mediated endocytosis did not change the uptake of labelled albumin into tumour cells, but inhibited the uptake of transferrin which was used as positive control." (PMID 21676260, 2011).
tumor (continued). "Higher loading ratios of drug to albumin had been shown to lead to accumulation in the liver, rather than in the tumour." (PMID 21676260, 2011). "In our previous study we developed methotrexate-human serum albumin conjugated (MTX-HSA) nanoparticles a delivery system, and showed that they could be used to deliver cytotoxic drug to tumor cells more efficiently when compared with the free cytotoxic drug." (PMID 21845098, 2011). "Presence of micrometastatic tumor cells in liver may induce the kupffer cells to produce a variety of cytokines (IL-Ib, IL-6 ve TNF), which may modulate albumin synthesis by hepatocytes." (PMID 21176210, 2010). "Among these predictors, the serum albumin level may reflect the conditions of patients liver physiology, while the rest of other factors hint to the biology or characteristics of the HCC tumor per se." (PMID 19886989, 2009). "The nature of the relationship between circulating albumin concentration, tumour burden and the systemic inflammatory response has not been established." (PMID 15213726, 2004). "We have previously measured the global uptake of blood-borne albumin, and found that it was strongly correlated to the extracellular volume fraction of the tumour tissue and was not limited by the permeability of the microvascular wall." (PMID 12610516, 2003). "The destruction of the hepatic parenchyma by the tumor led to significant enzymatic alterations, characterized by the increase of AST, ALT and LDH, the cholestatic pattern with high level of gGT and AP, and low serum level of albumin and altered PA." (PMID 10772698, 2000). "In conclusion, this study has shown that a high perfusion flow enhances the delivery of melphalan into implanted tumour nodules and normal tissues, and a perfusate with low melphalan binding (no albumin) is preferred for maximum uptake of drug by the tumour." (PMID 9099965, 1997). "The increased tumour level may arise from an increased uptake of FFA arising from a weakening of the bonds between FFA and albumin." (PMID 1764364, 1991). "Unlike albumin secretion, however, exposure of hepatic tumour cells to 2% DMSO did not further increase (but slightly decreased) extracellular AFP accumulation." (PMID 6194807, 1983). "But serum albumin level was significantly lower in the MPR group than in the non-MPR group (39.7 ± 4.4 vs. 43.2 ± 3.3 g/L, P = 0.024), which may be attributed to multiple factors such as hepatic function and tumor-related metabolic consumption." (PMID 41601630, 2026). "However, the HCC patient dataset from TCGA showed that ALB mRNA levels in nontumor and paired tumor tissue samples were not notably different, with the tumor group showing a slightly lower level." (PMID 40186033, 2025). "Additionally, the maximum tumor size was significantly larger in the non-curative group (5.1 [3.1–10.7] vs. 8.3 [5.3–12.0] cm, p = 0.010) and albumin levels were significantly higher in the curative group (4.3 [3.9–4.5] vs. 4.0 [3.6–4.2] g/dL, p < 0.001)." (PMID 40507275, 2025). "Furthermore, albumin is recruited by the tumor cells via albumin receptors such as SPARC (osteonectin) and gp60 (albondin) highly expressed on tumor cells; additionally, the aggressive tumor cells exploited albumin protein as a food and nutrients source to satisfy their needs for growth." (PMID 40908968, 2025). "Among the proteomic markers, elevated levels of serum ceruloplasmin, MYO1B, salivary CPLANE1, serum albumin, HSP 27, gamma actin, SCC 1, and A4, serum SNCG and SCCAg and immune cell markers such as, IL‐6, TNF‐α, and CD4 + T cell were suitable proteomic tumor markers in detecting OSCC." (PMID 40256126, 2025). "Besides, the albumin nanoparticle has been proven as a clinically successful delivery system that possesses several advantages, such as greater cellular uptake by tumor cells, lack of toxicity, and ease of availability as compared to other nanocarriers." (PMID 39801754, 2025).